SCARB1 (scavenger receptor class B member 1)
Diseases named in the same sentence as SCARB1 in open-access papers (continued):
Sharing a sentence is not in itself a finding about the gene and the disease.
B cell lymphoma (4 papers, 2017 to 2021). "Collectively, these data confirm that HDL NP efficacy against B cell lymphoma cell lines can be replicated in primary human SCARB1-positive B cell lymphoma cells ex vivo." (PMID 33208460, 2021). "Similar to B cell lymphoma cells, addition of the SCARB1 blocking Ab reduced binding of fluorescent DiI HDL NPs to SR-786, SUDHL1, and U937 cells and protected against HDL NP–induced cell death." (PMID 33208460, 2021). "We have demonstrated that certain B cell lymphomas highly express SCARB1, and targeted treatment with the HDL NPs potently induces in vitro and in vivo cell death by inhibiting cholesterol ester uptake and reducing cell cholesterol." (PMID 33208460, 2021). "In a mouse model of B cell lymphoma, dysfunctional NK cells expressed the lipid scavenging receptors CD36 and Scavenger Receptor Class B Member 1 (Scarb1) had elevated lipid droplet content." (PMID 34090499, 2021). "To best determine potential clinical relevance, we investigated expression of SCARB1 and whether HDL NPs induce cell death in primary B cell lymphoma cells derived from fresh patient tissue." (PMID 33208460, 2021).
breast tumors (4 papers, 2013 to 2016).
colitis (4 papers, 2018 to 2023). Inflammation of the colon. "Expression of two key SAA receptors (Fpr2 and Scarb1) was also elevated in the colon tissue of LysMCre;Arntfl/fl mice, reinforcing a potential role for SAA in colitis." (PMID 30455703, 2018).
female infertility (4 papers, 2018 to 2023). Diminished or absent ability of a female to achieve conception. "Mice deficient in the HDL receptor, encoded by Scarb1, are a model of female infertility linked to dysfunctional HDL." (PMID 36596339, 2022). "Some human genetic alterations in SCARB1 adversely impact cholesterol metabolism in the ovaries, thereby reducing fertility, and although some SCARB1 single-nucleotide polymorphisms are associated with human female infertility, underlying mechanisms are not known." (PMID 36596339, 2022).
heart failure (4 papers, 2017 to 2025). Inability of the heart to pump blood at an adequate rate to meet tissue metabolic requirements. "Interestingly, Scarb1−/− mice that are deficient in scavenger receptor class B, type 1 are characterized by more pronounced cardiac hypertrophy, cardiac dysfunction, and heart failure under conditions of pressure overload." (PMID 30871282, 2019). "Vascular density decreased following by TAC-induced heart failure, which is alleviated by Scarb1 CKO." (PMID 40772900, 2025). "In vitro and spatial omics analyses confirmed the role of SCARB1 in ECs and cell-cell interaction during heart failure progression." (PMID 40772900, 2025). "Heart failure was induced by performing TAC after tamoxifen administration in Scarb1 CKO and control mice." (PMID 40772900, 2025). "We clarified that FB-EC interactions through Scarb1 are critical for EC pathologic changes during heart failure development, using scRNA-seq and spatial omics analysis." (PMID 40772900, 2025). "Supporting this, both SCARB1 inhibition and EC-specific Scarb1 KO mitigated TAC-induced heart failure and cardiac fibrosis, identifying SCARB1 on ECs as a pivotal factor in heart failure progression and a potential therapeutic target." (PMID 40772900, 2025). "•Both EC-specific Scarb1 knockout and pharmacologic inhibition of SCARB1 significantly improved cardiac function and reduced fibrosis in pressure overload-induced heart failure models." (PMID 40772900, 2025). "This study investigated EC-fibroblast interactions mediated by Scarb1 using single-cell RNA-sequencing analysis in a mouse heart failure model." (PMID 40772900, 2025). "EC-specific Scarb1 knockout and systemic SCARB1 inhibition attenuated heart failure progression." (PMID 40772900, 2025). "Finally, we complemented these data with spatial transcriptomic analyses and in vivo/in vitro functional assays, thereby solidifying the link between SCARB1 in ECs and heart failure progression." (PMID 40772900, 2025). "Furthermore, we focused on Scarb1 expressed in ECs based on cell-cell interaction analysis and proposed that Scarb1 could be a novel therapeutic target for heart failure." (PMID 40772900, 2025). "Consequently, we hypothesize that Scarb1 expression in ECs, when stimulated by FBs, exacerbates heart failure due to enhanced fibrotic activity." (PMID 40772900, 2025). "Indeed, our data suggest that SCARB1 activation in ECs promotes an endothelial-mesenchymal transition–like state, and inhibition of SCARB1 reversed these phenotypes both in vitro and in vivo, highlighting the critical contribution of pathologic EC changes to heart failure progression." (PMID 40772900, 2025). "To verify whether SCARB1 receptors in ECs could be the therapeutic target for heart failure, we administered the SCARB1-specific inhibitor, BLT-152 daily to TAC-induced heart failure mice." (PMID 40772900, 2025). "To examine whether Scarb1 is actually a critical pathologic gene in mouse heart failure models, we generated EC-specific Scarb1 knockout mice (Scarb1 CKO) by crossing Cdh5-CreERT2 mice expressing EC-specific Cre induced by tamoxifen with Scarb1-flox mice." (PMID 40772900, 2025). "Echocardiography revealed that EC-specific Scarb1 KO significantly improved LVEF dysfunction compared to that in control TAC mice, restoring LVEF to pre-TAC levels and suggesting that Scarb1 in ECs plays a critical role in the progression of TAC-induced heart failure." (PMID 40772900, 2025). "Despite BLT-1 administration and Scarb1 CKO not preventing adaptive hypertrophy, they ultimately preserved cardiac function, suggesting that blocking SCARB1 in ECs prevents the transition to heart failure." (PMID 40772900, 2025). "However, HDL uptake in the liver was not altered by SCARB1 inhibition, indicating that simple changes in HDL influx are insufficient to explain the mitigation of heart failure." (PMID 40772900, 2025).
Hepatic steatosis (4 papers, 2017 to 2025). Steatosis is a term used to denote lipid accumulation within hepatocytes. "Thus, FGF19 and NGM282 appear to selectively modulate LXR signaling, upregulating canonical LXR target genes (Abcg5, Abcg8, Scarb1, Srebf1, Fasn, Scd1, Srebf2, and Scap) without inducing hepatic steatosis." (PMID 30679232, 2019).
liver cancer (4 papers, 2023 to 2026). An epithelial or non-epithelial malignant neoplasm that arises from the liver. "Cancer tissues express high levels of SCARB1, and this expression is associated with the differentiation status of liver cancer cells." (PMID 39453509, 2024).
renal cell carcinoma (4 papers, 2013 to 2024). "This SNP is in linkage disequilibrium with SCARB1-rs4765623 that has been associated with renal cell carcinoma." (PMID 24391818, 2013).
hepatitis C (3 papers, 2010 to 2021). "Additionally, women generally have better outcomes of HCV infection, perhaps related to estrogen, leading us to speculate on the role of estrogen-mediated expression of SCARB1 in outcomes of Hepatitis C infection." (PMID 20085651, 2010).
hyperalphalipoproteinemia (3 papers, 2012 to 2020). An autosomal dominant genetic condition caused by mutation(s) in the CETP gene, encoding cholesteryl ester transfer protein. "A decrease in the content of LCAT and SCARB1 transcripts may be suggested to result in the diminished flow of cholesteryl ester to the liver, thus contributing to hyperalphalipoproteinemia." (PMID 33269026, 2020). "A study of women with hyperalphalipoproteinemia also showed that SCARB1 protein was inversely correlated with HDL-C levels and HDL size, which suggesting that the SCARB1 in human may partly play the similar role as in the animals." (PMID 22583964, 2012).
hypospadias (3 papers, 2018 to 2024). Hypospadias is the displacement of the urethral meatus on the ventrum of the penis. "Moreover, three studies found that key enzymes involved in testosterone synthesis, represented by Cyp11a1, Cyp17a1, Hsd3b, Scarb1, Star, Hsd17b3 and Srd5α2, were significantly reduced at the genetic level in DBP- or DEHP-induced hypospadias male fetal rats." (PMID 39698037, 2024).
osteoporosis (3 papers, 2021 to 2025). A condition of reduced bone mass, with decreased cortical thickness and a decrease in the number and size of the trabeculae of cancellous bone (but normal chemical composition), resulting in increased fracture incidence. "FMO4 and NOV were associated with a decreased risk of osteoporosis, whereas MAP2K5, PSMA4, SCARB1 and VEGFA were linked to an increased risk." (PMID 40764749, 2025). "Due to this compensatory hormonal control, these Scarb1 null mice are not prone to osteoporosis in general but instead demonstrated higher bone mass associated with enhanced bone formation." (PMID 34899306, 2021).
colon tumour (2 papers, 2020 to 2023). "Three of the eight colonic tumor-related genes, ABCA1, PLA2G7, and SCARB1, were significantly correlated with GLS, the main enzyme for glutamate metabolism." (PMID 36843944, 2023).
kidney cancer (2 papers, 2021 to 2022). Primary or metastatic malignant neoplasm involving the kidney. "Intersecting the DeCAF results with kidney cancer GWAS data revealed a tsQTL at rs4765621 (FDR = 6.02−8) that colocalized with a genome-wide significant risk variant (p value = 3.33−12) for SCARB1." (PMID 35804456, 2022).
lung adenocarcinoma (2 papers, 2020 to 2021). A carcinoma that arises from the lung and is characterized by the presence of malignant glandular epithelial cells. "Another recurrent case (n = 4) was found in stomach, esophageal and lung adenocarcinoma, where SCARB1, a high-density lipoprotein (HDL) receptor, was overexpressed through fusion with NCOR2 due to tandem duplications on chromosome 12q24." (PMID 33097743, 2020).
lymph node metastasis (2 papers, 2018 to 2023). "In brief, elevated SCARB1 expression was significantly associated with lymph node metastasis, tumor stage, and the survival rate of patients." (PMID 37644041, 2023).
medulloblastoma (2 papers, 2018 to 2024). A malignant, invasive embryonal neoplasm arising from the cerebellum. "High expression of SCARB1 was associated with shorter overall survival in medulloblastoma patients." (PMID 29352211, 2018). "As SCARB1 is a negative prognostic factor in several cancers, we next analysed the effect of SCARB1 on patient outcomes in medulloblastoma." (PMID 29352211, 2018). "We analysed the expression of the SCARB1 gene in medulloblastoma, a tumour driven by aberrant activation of the SHH signalling pathway." (PMID 29352211, 2018). "In line with this we found that overexpression of SCARB1 in medulloblastoma corresponds to poor prognosis." (PMID 29352211, 2018). "We demonstrate uptake of HDL NPs in SCARB1 expressing medulloblastoma cells and depletion of cholesterol levels in cancer cells." (PMID 29352211, 2018). "Analysis of a large cohort of medulloblastoma patients indicates that SCARB1 is expressed in medulloblastoma cells and particularly enriched in the SHH subtype." (PMID 29352211, 2018). "We demonstrate that SHH-subtype medulloblastoma overexpresses SCARB1 when compared with other molecular subtypes." (PMID 29352211, 2018). "Furthermore, analysis of patient samples revealed an enrichment of several hedgehog pathway genes, such as GLI2, GLI3 and HHIP in cells from medulloblastoma patients expressing high SCARB1 levels." (PMID 29352211, 2018). "Analysis using the Northcott dataset revealed that SCARB1 was most highly expressed in SHH subtype medulloblastoma with a significant number of SHH subtype patient samples expressing SCARB1 >1 Log2 fold change when compared to the median (i.e., greater than twice the median expression value)." (PMID 29352211, 2018). "These cell lines expressed SCARB1, supporting our findings from medulloblastoma patient samples." (PMID 29352211, 2018). "After uncovering a potential role for the HDL receptor, SCARB1, in SHH-driven medulloblastoma, we tested the effect of synthetic HDL NPs on SHH-driven cancer cells." (PMID 29352211, 2018).
bipolar disorder (1 paper, 2023). A disorder of the brain that causes unusual shifts in mood, energy, activity levels and the ability to carry out day-to-day tasks. "Despite SCARB1 is a receptor of lipophilic ligands, including phospholipids, there are no credible data about relation of exactly SCARB1 to schizophrenia, albeit changing of phospholipids profile was established in metabolomic assay of patients with schizophrenia and bipolar disorder." (PMID 36747015, 2023).
chronic hepatitis C (1 paper, 2016). "We examined the association of single nucleotide polymorphisms(SNPs) of the SCARB1 gene, which encodes SR-BI, with virologic responses to pegylated interferon-based treatment in Asian chronic hepatitis C(CHC) patients." (PMID 27561198, 2016).
cutaneous melanoma (1 paper, 2023). A primary melanoma arising from atypical melanocytes in the skin. "Cholesterol metabolic genes such as SCARB1, were expected to contribute to the diagnosis and precision treatment of both ccRCC and skin cutaneous melanoma." (PMID 37801479, 2023). "The SCARB1-mediated cholesterol-dependent metabolism occurred both in ccRCC and skin cutaneous melanoma." (PMID 37801479, 2023). "We found that besides ccRCC (KIRC for cancer id), skin cutaneous melanoma (SKCM) also exhibited the SCARB1-mediated exogenous cholesterol dependent characteristics." (PMID 37801479, 2023). "In addition, we also found the exogenous cholesterol dependence of ccRCC, which count on SCARB1 mediated high-density lipoprotein (HDL) intake, also existed in skin cutaneous melanoma (SKCM)." (PMID 37801479, 2023).
dengue (1 paper, 2019). "The interaction between apolipoprotein A-I and the scavenger receptor class B type I (SCARB1), also known as SR-BI, promotes DENV infections, necessitating further research in order to elucidate the functional importance of lipoproteins in dengue pathogenesis." (PMID 31466307, 2019).
esophageal carcinoma (1 paper, 2022). A primary or metastatic malignant neoplasm involving the esophagus. "Further, CTSL, FURIN, NRP1 and SCARB1 gene expression levels were significantly higher in esophageal carcinoma (ESCA) samples in comparison to their normal matches." (PMID 35970857, 2022).
follicular lymphoma (1 paper, 2021). Follicular lymphoma is a form of non-Hodgkin lymphoma characterized by a proliferation of B cells whose nodular structure of follicular architecture is preserved. "In addition, SCARB1 expression in follicular lymphoma (FL) was also investigated." (PMID 33208460, 2021).
hypersplenism (1 paper, 2024). Overactive functioning of the spleen, resulting in excessive destruction of blood cells. "The expression of SCARB1, ALOX15, STAT6, and IL4 was up-regulated in hypersplenism, while the PPARγ expression was down-regulated." (PMID 39620221, 2024).
Immunodeficiency (1 paper, 2025). Failure of the immune system to protect the body adequately from infection, due to the absence or insufficiency of some component process or substance. "Cg14849578 was also reported to be associated with HIV and it is possible that SCARB1 interacts with immunodeficiency and HIV or share a common pathway leading to CKD." (PMID 39448372, 2025).
mastitis (1 paper, 2023). Inflammation of breast tissue during lactation or postpartum due to an obstructed duct or infection. "To understand the importance of the SCARB1 receptor in recognizing pathogens and activating downstream signaling; we first detected the expression status of SCARB1 in mammary gland tissue of healthy animals and animals with mammary gland infection/mastitis." (PMID 36604713, 2023). "The relationship between SCARB1 and MAPK1 in E. coli-induced mastitis is an interesting finding." (PMID 36604713, 2023).
nephrosclerosis (1 paper, 2022). Hardening of the kidney due to infiltration by fibrous connective tissue (fibrosis), usually caused by renovascular diseases or chronic hypertension. "Our results showed that two SNPs in the SCARB1 gene, rs10846744, and rs838880, were significantly linked to the susceptibility to nephrosclerosis." (PMID 35586043, 2022). "Most notably, rs10846744 and rs838880 in SCARB1 showed significant odds ratios (OR) of 0.66 (0.51–0.87), p = 0.003 and 1.48 (1.11–1.96), p = 0.007 for nephrosclerosis risk." (PMID 35586043, 2022). "We showed that SCARB1 for the risk of nephrosclerosis, PLA2G7 and, especially, PLA2G4A for the CV risk in these patients, are loci that harbor genetic variants whose identification could be of utility in the management of this CKD." (PMID 35586043, 2022). "We screened 1,209 nephrosclerosis patients and controls for 86 tag-SNPs that were identified in the SCARB1, PLA2G4A, and PLA2G7 gene loci." (PMID 35586043, 2022).
preeclampsia (1 paper, 2025). Preeclampsia is a hypertensive disorder of pregnancy that is characterized by new-onset hypertension with proteinuria presenting after 20 weeks of gestation, and depending on mild or severe forms may initially present with severe headache, visual disturbances, and hyperreflexia. "SCARB1, encoding the main receptor mediating lipoprotein particle transcytosis, showed increased expression in preeclampsia in SCT (95th percentile CPM: Ctrl = 176.7; PE = 271.5, p = 3.00e-07) and EVT (95th percentile CPM: Ctrl = 265.1; PE = 389.2, p = 0.037) clusters." (PMID 41446579, 2025).
Senile plaques (1 paper, 2018). Senile plaques are extracellular deposits of amyloid in the gray matter of the brain. "However, amyloid scavenger receptor class B member 1 (SR-B1) density was significantly decreased in the TG-Ctrl mice, but not in the TG-EE mice, suggesting that cognitive stimulation had an effect on the formation of a cognitive reserve that could prevent the accumulation of senile plaques." (PMID 30319394, 2018).
Thyroid (1 paper, 2022). "Thyroid hormones also strongly induce the gene and protein expression of Apo A1 and scavenger receptor class B member 1 (SRB1), thereby increasing the cholesterol outflow of peripheral tissues into HDL in the cholesterol reverse transport pathway." (PMID 36296646, 2022).